WDTC1 (WD and tetratricopeptide repeats 1)
Description:
May function as a substrate receptor for CUL4-DDB1 E3 ubiquitin-protein ligase complex.
Synonyms: KIAA1037; ADP; DCAF9
Tractability: PROTAC: ubiquitination databases record sites on it; its protein half-life has been measured.
Gene: Protein-coding gene on chromosome 1 (27,233,776 to 27,308,711, forward strand). Ensembl gene ENSG00000142784.
Subcellular location (Human Protein Atlas): Vesicles; Golgi apparatus
Pathways (Reactome):
Metabolism of proteins: Neddylation
Gene Ontology:
Molecular function: protein binding; enzyme inhibitor activity; histone binding; histone deacetylase binding
Biological process: negative regulation of adipose tissue development; protein ubiquitination
Cellular component: Cul4A-RING E3 ubiquitin ligase complex; Cul4B-RING E3 ubiquitin ligase complex; Cul4-RING E3 ubiquitin ligase complex; nucleoplasm; cytosol; nucleus
Genetic constraint (gnomAD): Loss-of-function variants: 12 observed, 79.1 expected, observed/expected ratio (o/e) 0.15, 90% interval 0.096 to 0.25. The upper end of that interval is the gene's LOEUF score, 0.25, which puts it in group 1 of 6, group 1 being the genes least tolerant of losing a copy. Missense variants: 511 observed, 946.09 expected, observed/expected ratio (o/e) 0.54, 90% interval 0.5 to 0.58. Synonymous variants: 326 observed, 368.88 expected, observed/expected ratio (o/e) 0.88, 90% interval 0.81 to 0.97.
Homologues: Orthologues: macaque WDTC1 (99% identical), dog WDTC1 (99% identical), guinea pig WDTC1 (99% identical), rabbit WDTC1 (99% identical), rat Wdtc1 (97% identical), mouse Wdtc1 (97% identical), pig WDTC1 (83% identical), zebrafish wdtc1 (81% identical), tropical clawed frog wdtc1 (79% identical), chimpanzee WDTC1 (75% identical), Drosophila melanogaster adp (36% identical), Caenorhabditis elegans adpr-1 (25% identical). Paralogues in human: DCAF6 (27% identical), DCAF8 (21% identical), DCAF8L2 (20% identical), DCAF8L1 (19% identical), DCAF5 (17% identical).
Diseases named in the same sentence as WDTC1 in open-access papers:
WDTC1 is named in the same sentence as 17 diseases in open-access papers, as found by Europe PMC text mining. Sharing a sentence is not in itself a finding about the gene and the disease. The quoted sentences say what the papers report.
Obesity (6 papers, 2019 to 2025). Accumulation of substantial excess body fat. "WDTC1 is an obesity-linked gene which appears to inhibit fat formation in a dosage-sensitive manner in both animals and humans." (PMID 31839790, 2019). "Mutation in Adipose, the Drosophila homolog of WDTC1, caused obesity in Drosophila." (PMID 37691821, 2023). "Remarkably, WDTC1 SNP variants were defined as human obesity markers." (PMID 35204721, 2022). "WD40 and tetratricopeptide repeats 1 (WDTC1) is an anti-obesity factor conserved from worms to mammals." (PMID 37691821, 2023). "Interestingly, the anti-obesity factor WDTC1 (DCAF9), an SR of CRL4, reduces lipid production and suppresses adipogenesis via the CRL4WDTC1 ligase in 3T3-L1 cells." (PMID 40149914, 2025). "Among them, WDTC1 is very intriguing, as it is an evolutionally conserved anti-obesity factor." (PMID 37691821, 2023). "WDTC1 is a WD40-containing protein that functions as an anti-obesity factor." (PMID 37691821, 2023). "WDTC1 is an anti-obesity gene and inhibits adipogenesis by the CRL4WDTC1 E3 ligase." (PMID 37980532, 2023). "In humans, the expression level of WDTC1 is negatively correlated with obesity." (PMID 37691821, 2023).
colorectal cancer (1 paper, 2023). A primary or metastatic malignant neoplasm that affects the colon or rectum. "In colorectal cancer, WDTC1 can function as the oncogene to facilitate cancer development." (PMID 37980532, 2023).
juvenile polyposis syndrome (1 paper, 2010). Juvenile gastrointestinal polyposis (JIP) is a rare condition characterized by the presence of juvenile hamartomatous polyps in the gastrointestinal (GI) tract. "Since we found significant cancer-related pathways associated only with BMPR1A but not with WDTC1 or EHD3, and in addition germline mutations in BMPR1A are a known risk factor for juvenile polyposis syndrome, we chose BMPR1A for additional functional assays." (PMID 21203531, 2010).
renal cell carcinoma (1 paper, 2023). "Among the screened proteins, we found WDTC1 was significantly downregulated in KIRC, indicating that WDTC1 may be an interacting protein of USP3 in renal cell carcinoma." (PMID 37980532, 2023).
tumor (5 papers, 2017 to 2023). "ELF5 acts as a tumor suppressor though activating the transcription of USP3 to stabilizing WDTC1 in RCC." (PMID 37980532, 2023). "In-vivo studies established that WDTC1 inhibited RCC tumor growth." (PMID 37980532, 2023). "The hazard ratios of LCLAT1 and CCDC43 are positive, indicating the anti- survival function of these genes, while the coefficients of other 5 genes are negative, including ENSG00000269386 (RAB11B-AS1), TOM1L2, AMPD3, MINK1 and WDTC1, indicating that they may be tumor suppressor genes." (PMID 28331188, 2017). "Furthermore, WDTC1 upregulation significantly suppress RCC cell proliferation, migration, invasion, angiogenesis, and RCC tumor progression in vivo." (PMID 37980532, 2023).
cancer (2 papers, 2010 to 2023). A tumor composed of atypical neoplastic, often pleomorphic cells that invade other tissues. "Furthermore, looking at intersections between both cancer types we found BMPR1A, WDTC1 (WD and tetratricopeptode repeats 1) and EHD3 (EH-domain containing 3) mutated in both tumors." (PMID 21203531, 2010).
WDTC1 also shares sentences with these, for which no sentence is quoted: infection (3 papers); glioma (2); viral infection (2); Alzheimer disease (1); colon cancer (1); epilepsy (1); experimental autoimmune encephalomyelitis (1); gastric cancer (1); multiple sclerosis (1); prostate carcinoma (1); prostate tumour (1).